FAM219A (family with sequence similarity 219 member A)
Synonyms: C9orf25; bA573M23.5; FLJ39031
Tractability: PROTAC: its protein half-life has been measured.
Gene: Protein-coding gene on chromosome 9 (34,398,184 to 34,458,591, reverse strand). Ensembl gene ENSG00000164970.
Subcellular location (Human Protein Atlas): Golgi apparatus; Nucleoplasm; Vesicles
Genetic constraint (gnomAD): Loss-of-function variants: 7 observed, 22.35 expected, observed/expected ratio (o/e) 0.31, 90% interval 0.18 to 0.59. The upper end of that interval is the gene's LOEUF score, 0.59, which puts it in group 2 of 6, group 1 being the genes least tolerant of losing a copy. Missense variants: 166 observed, 239.56 expected, observed/expected ratio (o/e) 0.69, 90% interval 0.61 to 0.79. Synonymous variants: 93 observed, 99.27 expected, observed/expected ratio (o/e) 0.94, 90% interval 0.79 to 1.11.
Homologues: Orthologues: pig FAM219A (100% identical), chimpanzee FAM219A (99% identical), macaque FAM219A (99% identical), rat Fam219a (99% identical), dog FAM219A (91% identical), guinea pig FAM219A (90% identical), mouse Fam219a (90% identical), zebrafish fam219aa (88% identical), zebrafish fam219ab (86% identical), rabbit FAM219A (64% identical). Paralogues in human: FAM219B (43% identical).